VDAC3 (voltage dependent anion channel 3)
Diseases named in the same sentence as VDAC3 in open-access papers (continued):
Sharing a sentence is not in itself a finding about the gene and the disease.
tumor (13 papers, 2016 to 2025). "In contrast, VDAC3-CAF-C1 and ITM2C-CAF-C5 were significantly enriched in pathways associated with tumor-related inflammatory responses." (PMID 40145099, 2025). "Increased nuclear translocation of EGR1 was found to enhance the transcription activity of miR-3928 v and downregulated expression of voltage-dependent anion channel 3, a tumor-suppressor, thereby increasing malignancy of LC cells." (PMID 34409922, 2021). "We next investigated the effect of VDAC3 depletion on cell growth in xenograft tumor models in immunodeficient mice." (PMID 30787272, 2019). "VDAC3 knockdown suppressed growth of HCT116 tumor cells, which is in accord with the result of PKM2 knock down." (PMID 30787272, 2019). "We further investigated the effect of PKM2 and VDAC3 on cell survival and tumor development." (PMID 30787272, 2019). "As mitochondrial PKM2–VDAC3 contributes to tumor development, we investigated mitochondrial PKM2 and VDAC3 to determine whether they are upregulated in early stages of tumorigenesis in a mouse model." (PMID 30787272, 2019). "In tumor cells, succinylation of PKM2 at K433 stabilizes voltage-dependent anion channel 3 (VDAC3), leading to increased mitochondrial permeability and ATP production, which supports cell survival during glucose starvation." (PMID 39781339, 2025). "Compound 8 blocks the interaction of PKM2 and VDAC3, and blockage of PKM2 mitochondrial translocation by this molecule inhibits tumor growth in vivo." (PMID 30787272, 2019). "Deletion of VDAC3 significantly increases cell resistance to anti-tumor agent Erastin, which targets VDAC2 and VDAC3." (PMID 29854282, 2018). "IHC staining analysis suggested that TRADD, VDAC3, JMJD7-PLA2G4B, and TRAF2 expression levels were upregulated in COAD tumor tissues compared with those in normal gastric tissues at the protein level, which was consistent with the expression pattern of the genes." (PMID 36505813, 2022). "Furthermore, the mRNA expression of FBXW7 was decreased and that of WDR5 was increased in BDNF-AS-overexpressing tumor tissues, but VDAC3 expression was not significantly changed." (PMID 35280682, 2022).
infection (3 papers, 2013 to 2022). The state of being infected such as from the introduction of a foreign agent such as serum, vaccine, antigenic substance or organism. "Silencing of VDAC3 expression robustly increased their levels, especially after infection." (PMID 36016340, 2022). "To study the role of VDAC3 in virus-induced mitochondrial ROS generation, we mock infected or infected Vero-shVDAC3 cells, RD-shVDAC3 cells, and their NTC-expressing counterparts with EV71, and determined total cellular and mitochondrial ROS formation at 24 h post-infection." (PMID 36016340, 2022).
neurological disorders (2 papers, 2025). "Functioning as a crucial mitochondrial outer membrane channel protein and a recognized ferroptosis related gene, VDAC3 has recently garnered substantial research attention in neurological disorders." (PMID 40901058, 2025).
adenocarcinoma (1 paper, 2014). A common cancer characterized by the presence of malignant glandular cells. "Interestingly, the three genes (VDAC1, VDAC2, and VDAC3,) coding for voltage-dependent anion channels (VDACs), which is a class of porin ion channel located on the outer mitochondrial membrane, were all down-regulated in adenocarcinoma." (PMID 24466154, 2014).
VDAC3 also shares sentences with these, for which no sentence is quoted: hepatocellular carcinoma (2 papers); Hypothermia (2); lung carcinoma (2); Alzheimer disease (1); amyotrophic lateral sclerosis (1); atherosclerosis (1); brain disease (1); hypopharyngeal squamous cell carcinoma (1); multiple sclerosis (1); neurodegenerative disease (1); renal carcinoma (1); thyroid tumor (1).